MCM3 (minichromosome maintenance complex component 3)
Diseases named in the same sentence as MCM3 in open-access papers (continued):
Sharing a sentence is not in itself a finding about the gene and the disease.
hepatocellular carcinoma (12 papers, 2018 to 2025). A malignant tumor that arises from hepatocytes. "Elevated MCM3 expression has been reported in, hepatocellular carcinoma, oral squamous cell carcinoma, and papillary thyroid carcinoma." (PMID 41502508, 2025). "To understand the mechanism by which MCM3 promotes hepatocellular carcinoma, we screened the TCGA dataset and performed GO and KEGG analyses on these DEGs." (PMID 39991578, 2025). "Elevated MCM3 expression has been observed in multiple cancers, such as papillary thyroid carcinoma, hepatocellular carcinoma, and endometrial carcinoma." (PMID 41502508, 2025). "Following the synthesis of CCNB1, CDC20, CDC7, BUB1B, and MCM3 have been examined in hepatocellular carcinoma (HCC) samples." (PMID 36497125, 2022). "In previous studies, MCM3 was shown to act as a proliferation marker and regulate programmed cell death in tumour cells, such as hepatocellular carcinoma, tubo-ovarian high-grade serous carcinoma, oral squamous cell carcinoma, odontogenic cysts and ameloblastoma." (PMID 38698811, 2024). "The overexpression of MCM3 in tumor tissues predicts poor survival in hepatocellular carcinoma." (PMID 35627203, 2022). "Previous studies also reported that MCM3 hypomethylation could increase its expression in hepatocellular carcinoma and osteosarcoma, and was negatively associated with prognosis." (PMID 36133906, 2022). "Recent studies have shown that elevated expression of MCM3 in tumor tissues of hepatocellular carcinoma patients predicted worse overall survival, while RPA1 being demonstrated as a candidate oncogene which influences tumor biological behaviors in many cancers including colon cancer." (PMID 31581454, 2019). "Genes, such as MCM3, MCM5, MCM7, and DSN1, are associated with the pathogenesis of various cancers, such as salivary gland cancer, cervical cancer, and hepatocellular carcinoma, through regulation of cell cycle, but these genes may be involved in progression of BRCA." (PMID 31311202, 2019).
medulloblastoma (11 papers, 2012 to 2025). A malignant, invasive embryonal neoplasm arising from the cerebellum. "The expression of MCM3 has also been associated with poor prognoses in malignant glioma and medulloblastoma." (PMID 35627203, 2022). "The expression of MCM3 was also associated with poor survival outcomes in medulloblastoma and malignant glioma." (PMID 34490114, 2021). "Another study demonstrated that MCM3 is overexpressed in medulloblastoma and is involved in tumour cell invasion and metastasis." (PMID 38698811, 2024). "Moreover, we discovered that MCM3 might affect varied biological processes such as apoptosis, autophagy, and ferroptosis and that MCM3 was correlated with immune components such as fibroblast and neutrophils, which were associated with overall survival in different medulloblastoma subtypes." (PMID 36133906, 2022). "First, we showed the upregulation of MCM3 in medulloblastoma (MB) at bulk and single-cell RNA sequence levels and revealed the potential role of MCM3 via DNA replication." (PMID 36133906, 2022). "In a previous research, it was showed that the high MCM3 expression enhances cell migration, cell growth, and the invasion ability of medulloblastoma cells." (PMID 34144903, 2022). "Previous studies have shown that overexpression of MCM3 enhances the cell growth, migration, and invasion of medulloblastoma cells." (PMID 34993142, 2021). "MCM3 expression has also been asssociated with poor prognosis in malignant glioma and medulloblastoma." (PMID 22805320, 2012). "Recently, high expressions of MCM3 in various cancers, such as head and neck squamous-cell carcinoma, colorectal, bladder, renal cell carcinoma, medulloblastoma, and ovarian cancer, correlated with malignant properties and cell proliferation, were determined in the literature." (PMID 39941813, 2025). "The overexpression of MCM2 and MCM3 increased the proliferation and migration of medulloblastoma." (PMID 28460433, 2017).
lung carcinoma (9 papers, 2014 to 2024). "Diseases associated with MCM3 include grade III astrocytoma and lung cancer." (PMID 34193281, 2021). "Consistently, our result showed that MCM3 was highly expressed in lung cancer, especially in LUSC, and high MCM3 level was significantly correlated with poor OS in all subtypes of lung cancer patients." (PMID 33936158, 2021). "Transcriptomic alterations that occur during lung cancer development include over-expressed cell cycle related genes like E2F3, BUB3, CDK4, MCM2, MCM3, and MCM7 as summarized by Powell and Borczuk." (PMID 26930711, 2016).
oral squamous cell carcinoma (9 papers, 2015 to 2025). "In another study, MCM3 was found to be a potential marker of cellular proliferation in oral squamous cell carcinoma." (PMID 33816217, 2021). "Thus, we conclude from our study that MCM3 could be a valuable marker in differential diagnosis of premalignant oral lesions and oral squamous cell carcinoma." (PMID 36611359, 2022). "The expression analysis of cyclin D1, Ki-67, MCM3 and MCM2 in oral squamous cell carcinoma to identify biomarkers is of interest." (PMID 38415027, 2023). "Therefore, it is ofinterest to document the expression of cyclin D, Ki-67, MCM3 and MCM2 in oral squamous cell carcinoma to glean biomarkers." (PMID 38415027, 2023).
ovarian carcinoma (9 papers, 2012 to 2026). A malignant neoplasm originating from the surface ovarian epithelium. "Another study in ovarian cancer showed that increased expression of MCM-3 and Ki-67 was associated with increased histological malignancy." (PMID 34671420, 2021). "It was found that low mRNA expression of MCM3 (HR 0.75 [0.58–0.97], P = 0.027) was associated with worse overall survival for ovarian cancer patients, as well as GINS2 (HR 0.75 [0.58–0.97], P = 0.026)." (PMID 31703725, 2019). "In ovarian cancer, an inverse association was found between expression of RBM3 and the minichromosome maintenance 3 (MCM3) gene and protein." (PMID 22805320, 2012). "The here observed inverse association of MCM3 and RBM3, both regarding their tumour-specific expression and impact on survival, is in line with previous in vivo and in vitro observations in ovarian cancer." (PMID 22805320, 2012). "Indeed, these findings are pointing to probable independent role of MCM3 in ovarian cancer disease progression." (PMID 40280979, 2025). "Microliposome maintenance (MCM) 2, MCM3, MCM4, MCM5, MCM6, and MCM7 are DNA replication regulators and are involved in the progression of multiple cancer types, but their role in ovarian cancer is still unclear." (PMID 34178669, 2021). "To validate the GSEA results, we then detected the expression of cell cycle (PCNA and PLK1), DNA replication (MCM2 and MCM3) and BER pathways-related proteins (PARP1 and PARP2) in ovarian cancer cells transiently overexpressed ARHGAP10." (PMID 27010858, 2016). "Taken together, these results further underscore the role of MCM3 as a negative predictor of ovarian cancer prognosis." (PMID 40280979, 2025).
prostate carcinoma (9 papers, 2009 to 2024). A carcinoma that arises from epithelial cells of the prostate gland. "Here, we report that MCM2, MCM3, MCM4, and MCM6 (MCM2/3/4/6) are elevated in human NEPC and high levels of MCM2/3/4/6 are associated with liver metastasis and poor survival in prostate cancer patients." (PMID 34172788, 2021). "MCM3 is upregulated in prostate cancer tissues samples with bone metastasis, mouse model showed that MCM3 is increased in mesenchymal-derived tumors." (PMID 31208444, 2019). "We found an elevated expression of the proliferation marker MCM3 in ARCaPM compared to ARCaPE cells and during the progression of prostate cancer from primary tumor to metastatic disease." (PMID 28424404, 2017). "In accord with our previous results, expression of MCM3 was significantly increased in primary tumors and further upregulated in bone metastases, suggesting a pivotal role of MCM3 in prostate cancer progression and metastasis." (PMID 28424404, 2017). "Semi-quantitative analysis of MCM3 expression in the different human prostate tissues showed the lowest MCM3 expression in normal tissue and the highest in high-grade prostate cancer." (PMID 28424404, 2017). "In our proteomics and Western blotting analyses, MCM3 was upregulated upon EMT in the ARCaP prostate cancer cell model." (PMID 28424404, 2017). "To assess the significance of our ARCaP EMT model for clinical prostate cancer progression, we evaluated the expression of MCM3 in normal prostate (n = 12), benign prostatic hyperplasia (BPH, n = 6), and primary prostate carcinoma tissues (n = 12)." (PMID 28424404, 2017). "The best in frame clone (AUC = 0.87) showed sequence homology to MCM3 that has been identified as immunogenic antigen in colon and prostate cancer." (PMID 19284601, 2009). "MCM3 is highly expressed in diverse types of malignancies, including breast cancer, ovarian cancer, colorectal cancer, and prostate cancer." (PMID 38698811, 2024). "Furthermore, immunohistochemical analysis of MCM3 protein levels in human prostate tissue specimens showed elevated expression in bone metastasis and advanced human prostate cancer tissue samples." (PMID 28424404, 2017). "This study identifies MCM3 as an upregulated molecule in mesenchymal phenotype of human prostate cancer cells and advanced human prostate cancer specimens, suggesting MCM3 may be a new potential drug target for prostate cancer treatment." (PMID 28424404, 2017). "Collectively, our data suggest a pivotal role of MCM3 in prostate cancer metastasis and a possible AR-MCM7-MCM3 interaction that may be responsible for the growth, metastasis, and androgen-repressed phenotype of late stage human prostate cancer." (PMID 28424404, 2017). "Moreover, it inhibited the invasion of prostate cancer cells and lowered the expression of MCM2/MCM3, PCNA, and CDK2." (PMID 37682177, 2023). "We selected MCM3 for further study based on lack of reports in the literature on the expression of MCM3 in prostate cancer, and on its critical importance in the cell cycle." (PMID 28424404, 2017). "MCM3 was observed to be absent in normal prostate, barely observed in benign tumor, and highly expressed in late stage prostate cancer." (PMID 28424404, 2017).
cervical cancer (7 papers, 2018 to 2023). A primary or metastatic malignant neoplasm involving the cervix. "The Kaplan-Meier curve and log rank test analyses revealed that the increased MCM3 mRNA levels were significantly associated with better overall survival (OS) (p < 0.05) of all of the patients with cervical cancer." (PMID 34671420, 2021). "A high MCM3 expression was significantly associated with better OS in patients with cervical cancer." (PMID 34671420, 2021). "We selected two proteins PRIM2 and MCM6, which have strong correlation with MCM3 and have different expressions in cervical cancer compared with normal cervical tissues." (PMID 34671420, 2021). "Specifically, MCM3 is significantly differentially expressed between patients in stage 1 and stage 3 cervical cancer with p value 0.0138." (PMID 34671420, 2021). "Despite the intensive study of MCM3 in many cancers, there is limited research regarding MCM3 in cervical cancer." (PMID 34671420, 2021). "In summary, this analysis shows that MCM3 is more highly expressed in cervical cancer than normal cervical tissues." (PMID 34671420, 2021). "ONCOMINE and GEPIA datasets were used to compare the expression level of MCM3 in cervical cancer with those in corresponding normal tissues." (PMID 34671420, 2021). "We used the TIMER database to explore the correlation between MCM3 and immune cell infiltration in cervical cancer." (PMID 34671420, 2021). "Although the role of MCM3 in the tumorigenesis and prognosis of several cancers has been partially confirmed, further bioinformatics analysis of cervical cancer has yet to be performed." (PMID 34671420, 2021). "In order to further study the potential mechanism of MCM3 in cervical cancer, we excavated the gene data coexpressed with MCM3 by the GEPIA database and LinkedOmics database." (PMID 34671420, 2021). "Next, we analyzed the correlation between the expression of MCM3 in cervical cancer and immune infiltration." (PMID 34671420, 2021). "We will further explore the potential mechanism of MCM3 in cervical cancer by clinical tissues and cervical cancer cell lines in in vivo and in vitro experiments." (PMID 34671420, 2021). "The results showed that MCM3 was significantly related to the purity of cervical cancer (R = 0.128, p = 3.23e − 02)." (PMID 34671420, 2021). "Herein, we investigated the expression patterns and survival data of MCM3 in cervical cancer patients from the ONCOMINE, GEPIA, Human Protein Atlas, UALCAN, Kaplan-Meier Plotter, and LinkedOmics databases." (PMID 34671420, 2021). "In our study, ONCOMINE datasets and the GEPIA database revealed that the expression of MCM3 was significantly higher in cervical cancer than in normal tissues." (PMID 34671420, 2021). "By studying the role of MCM3 in cervical cancer, it might provide a novel biomarker for drug development and repositioning on this cancer." (PMID 34671420, 2021). "However, it is currently limited to bioinformatics analysis, and more clinical tissue specimens and cell experiments are needed to further explore the role of MCM3 in the occurrence and progression of cervical cancer." (PMID 34671420, 2021). "Cervical cancer patients had good survival with high MCM3 expression." (PMID 34671420, 2021). "Not only that, cervical cancer patients with high mRNA expression of MCM3 may indicate longer overall survival but indicate shorter relapse-free survival." (PMID 34671420, 2021). "Bioinformatics analysis revealed that MCM3 might be considered a biological indicator for prognostic evaluation of cervical cancer." (PMID 34671420, 2021). "Importantly, the current study focuses on the analysis of exploring the expression and prognostic values of MCM3 in cervical cancer." (PMID 34671420, 2021). "We further analyzed the prognostic value of MCM3 in cervical cancers in the Kaplan-Meier Plotter." (PMID 34671420, 2021).
cervical cancer (continued). "Using RT‐PCR analysis, except for MCM3 and MCM5, MCMs are upregulated in cervical cancer in vitro and in vivo, which are critical in tumor progression." (PMID 36776764, 2023). "On that account, we propose that MCM3 and EVPL are promising candidate protein biomarkers for population-based cervical cancer screening." (PMID 37445651, 2023). "Pearson correlation analysis showed that the expression of MCM3 and PRIM2 or MCM6 in cervical cancer was obviously positive (R = 0.6387 and R = 0.5443, respectively)." (PMID 34671420, 2021). "Moreover, MCM3 may become the target of immunotherapy for cervical cancer in the future." (PMID 34671420, 2021). "The results indicate that MCM3, PRIM2, and MCM6 could be used for early detection of cervical cancer and may be used as indicators of prognosis." (PMID 34671420, 2021). "Hierarchical clustering and Gepia results indicated that the expression quantity of hub genes NDC80, TIPIN, MCM3, MCM6, POLA1, and PRC1 may determine the prognosis of cervical cancer." (PMID 33816217, 2021). "Interestingly, levels of members of the Minichromosome Maintenance (MCM) family (MCM2, MCM3, MCM4, MCM5, MCM6, MCM7) were found to be highly significantly increased in cervical cancer tissue from early and late stage patients as compared to healthy tissue." (PMID 29719595, 2018). "However, the expression and prognostic values of MCM3 in cervical cancer (CC) have not been well-studied." (PMID 34671420, 2021).
ameloblastoma (6 papers, 2015 to 2024). The most common odontogenic tumor, arising from the epithelial component of the embryonic tooth and usually affecting the molar-ramus region of the mandible or maxilla. "A previous study also reported a similar expression of Ki67 and MCM3 proliferation markers in a limited number of unicystic ameloblastomas in comparison with dentigerous cysts." (PMID 36483932, 2022). "Coincidentally, the expression levels of MCM2 and MCM3 are sensitive markers for predicting aggressive and recurrent behaviors of ameloblastoma." (PMID 28460433, 2017).
glioma (6 papers, 2014 to 2024). A benign or malignant brain and spinal cord tumor that arises from glial cells (astrocytes, oligodendrocytes, ependymal cells). "CNV analysis results confirmed that copy number variations of MCM7, MCM9, and MCM3 were significantly positively correlated with its expression in glioma." (PMID 36465369, 2022). "In this research, we uncovered that copy number variations of MCM7, MCM9 and MCM3 were significantly positively correlated with its expression in glioma." (PMID 36465369, 2022). "MCM3 expression found to be up-regulated in glioma and correlated with overall survival in WHO grade III." (PMID 25046975, 2014). "MCM3 expression was found to be up-regulated in glioma and correlated with overall survival in the grade III group." (PMID 25046975, 2014). "MCM3 expression was found to be up-regulated in glioma and correlated with overall survival in patients with WHO grade III tumor." (PMID 25046975, 2014). "Our findings demonstrated that the expression of MCM3 differed in different cell types and that there were differences in cell components among samples, which may be related to the heterogeneity of the glioma microenvironment." (PMID 38698811, 2024). "In addition, previous studies have demonstrated that essential nodes in crucial pathways may be specifically blocked to slow glioma progression, which further suggests that MCM3 may be a promising therapeutic target for LGG." (PMID 38698811, 2024). "The clinical correlation and independent prognostic significance of MCM3 were further analysed in the TCGA and CGGA lower-grade glioma (LGG) cohorts, and a prognostic nomogram was constructed." (PMID 38698811, 2024). "Most notably, MCM2, MCM3 and MCM7 aberrations in glioma tumors portend a particularly aggressive clinical behavior." (PMID 25046975, 2014). "An immunoreactive band of MCM2, MCM3 and MCM7 were seen in all six cases of gliomas, MCM2, MCM3 and MCM7 expressions were significantly higher in malignant tissues than in tissues with low malignant potential." (PMID 25046975, 2014). "In conclusion, the results suggest that MCM2, MCM3 and MCM7 play important roles in glioma tumor progression." (PMID 25046975, 2014). "To confirm the specificity of the qPCR results, we characterized MCM2, MCM3, MCM7, as well as β-actin as a loading control, in six glioma samples for which freshly frozen materials were available." (PMID 25046975, 2014). "MCM2, MCM3 and MCM7 proteins expression is also known to be an important tool for estimating tumor proliferation and a useful adjunct to the routinely used proliferation markers for glioma diagnosis." (PMID 25046975, 2014). "Thus the expression level of MCM2, MCM3 and MCM7 reveal information on the survival probability for patients with glioma beyond that revealed by grade alone." (PMID 25046975, 2014). "High expression of MCM 2, MCM3 and MCM7 mRNA correlated with poor outcome and may be clinically useful molecular prognostic markers in glioma." (PMID 25046975, 2014).
liver cancer (6 papers, 2019 to 2025). An epithelial or non-epithelial malignant neoplasm that arises from the liver. "A study of liver cancer showed that high expression of MCM3 was associated with tumor invasion and poor prognosis of liver cancer patients." (PMID 34671420, 2021). "We also found that the hub upregulated genes in this network—MCM3, BUB1B, DLGAP5, DIP5, ECT2—have been linked to liver cancer according to wide literature reports." (PMID 39628446, 2024). "Firstly, we investigated the immune infiltration of MCM3 in liver cancer." (PMID 39991578, 2025). "In the MCM family, abnormal expression of MCM2, MCM3, MCM4, MCM5, and MCM7 also results in reducing prognosis in liver cancer patients according to the HCCDB database." (PMID 32082966, 2019).